RUNDC1 (RUN domain containing 1)
Synonyms: DKFZp761H0421; RUND1
Tractability: PROTAC: ubiquitination databases record sites on it.
Gene: Protein-coding gene on chromosome 17 (42,980,552 to 42,995,142, forward strand). Ensembl gene ENSG00000198863.
Subcellular location (Human Protein Atlas): Nuclear speckles; Cytosol
Genetic constraint (gnomAD): Loss-of-function variants: 31 observed, 46.29 expected, observed/expected ratio (o/e) 0.67, 90% interval 0.5 to 0.9. The upper end of that interval is the gene's LOEUF score, 0.9, which puts it in group 3 of 6, group 1 being the genes least tolerant of losing a copy. Missense variants: 715 observed, 768.6 expected, observed/expected ratio (o/e) 0.93, 90% interval 0.87 to 0.99. Synonymous variants: 347 observed, 321.19 expected, observed/expected ratio (o/e) 1.08, 90% interval 0.99 to 1.18.
Homologues: Orthologues: chimpanzee RUNDC1 (99% identical), macaque RUNDC1 (98% identical), dog RUNDC1 (94% identical), rabbit RUNDC1 (93% identical), pig RUNDC1 (93% identical), rat Rundc1 (90% identical), mouse Rundc1 (89% identical), guinea pig RUNDC1 (79% identical), tropical clawed frog rundc1 (62% identical), zebrafish rundc1 (59% identical), Drosophila melanogaster CG3703 (36% identical), Caenorhabditis elegans rund-1 (28% identical).
Diseases named in the same sentence as RUNDC1 in open-access papers:
RUNDC1 is named in the same sentence as 2 diseases in open-access papers, as found by Europe PMC text mining. Sharing a sentence is not in itself a finding about the gene and the disease.
RUNDC1 shares sentences with these, for which no sentence is quoted: cancer (2 papers); leiomyoma (1).